CD80 (CD80 molecule)
Diseases named in the same sentence as CD80 in open-access papers (continued):
Sharing a sentence is not in itself a finding about the gene and the disease.
tumor (continued). "Sarcoma data from the TCGA were downloaded to analyze the lncRNAs positively correlated with immune checkpoint inhibitory molecules (CD274, CD80, CD86, PDCD1 LG2 and LGALS9), which accelerate the process of tumor cell immune evasion." (PMID 34178688, 2021). "Poly6 treatment also enhanced expression of DC maturation markers CD40, CD80, CD86, and MHC class II molecules in tumor and draining lymph node tissues in MC38-bearing mice." (PMID 33499256, 2021). "Our study additionally identified that within the tumour compartments, responding patients exhibited higher levels of GMZA, STING and fibronectin and reduced levels of CD80." (PMID 35083152, 2021). "The first was CTLA4, which binds CD80/CD86 to negatively regulate T-cell activation and blockade leads to anti-tumor immune responses." (PMID 34394102, 2021). "Abs to CTLA-4 block the inhibition of CD80/CD86-dependent T cell activation and in turn prolong anti-tumor activity." (PMID 34205484, 2021). "Both CD80 and CD28 blockade significantly impaired the anti-tumor efficacy of BI 853520, implying an important role for CD80 in regulating response to a FAK inhibitor." (PMID 31959281, 2020). "We found that tumor Tregs showed a higher frequency and MFI of CD80 than Tconv and peripheral Tregs from healthy donors (HD)." (PMID 32601304, 2020). "For example, checkpoint ligand-receptor pairs, such as tumor Treg CD80-Th17 cell CTLA4 and tumor Treg CD274-Th17 cell PDCD1, were identified in our study." (PMID 33584715, 2020). "CTLA-4 downregulates T-cell activation and inhibits its anti-tumor immune response by binding to co-stimulatory molecules on DCs (CD40, CD80, and CD86) and suppressing their ability in presenting foreign or tumor antigens." (PMID 32784928, 2020). "Our data also showed that YPF decreased the levels of TSLP, TSLPR, and OX40L, increased the expression of CD80, CD86, and MHC-II in DCs, and stimulated the maturation of DCs in tumor and adjacent tissues of mice bearing with HCC." (PMID 32351590, 2020). "Among the IRGs filtered, the CTLA-4 promotes immune escape of tumor cells by competitively binding to CD80 and CD86, blocking T cell activation and anti-tumor immune response of the body." (PMID 33031392, 2020). "Mechanistically, incubation of dendritic cells with tumor MV induced dendritic cell maturation with concordant upregulation of the co-stimulatory molecules CD80 and CD86, increasing their homing to the tumor-draining lymph nodes." (PMID 32731639, 2020). "Upon intra-peritumoral administration of CD80/86 + IL12 and OX40L mRNA-CARTs the mice showed a complete response at the treated tumor and systemic anti-tumor immune response, as seen by the regression of the untreated distal tumor." (PMID 33050070, 2020). "DCs pulsed with PDT-treated tumor cells exhibited an enhanced expression of co-stimulatory signals (CD80, MHC-II) and tumor-directed chemotaxis." (PMID 32178288, 2020). "We also observed that VV-iPDL1/GM significantly promoted tumor-infiltrating DC maturation, as evidenced by an increased expression of MHCII, CD80, CD86, and CD40." (PMID 32170083, 2020). "After 7 days, a fraction of the tumor was used for immunohistochemistry (IHC) to detect the expression of CD206 (M2-like marker), CD80, and CD11b (an M1-like marker)." (PMID 32548111, 2020). "Overexpression of EBV miR-BART1-5p in EBV-associated tumor cells can inhibit the expression of LY75, and promote tumor cells to get rid of the recognition and monitoring of CD4+ Th cells and CD80+ CTL cells." (PMID 32127936, 2020). "Checkpoint ligand-receptor pairs (e.g., tumor Treg CD80-Th17 cell CTLA4 and tumor Treg CD274-Th17 cell PDCD1) were identified." (PMID 33584715, 2020). "In terms of the surface expression quantitated through the median fluorescence intensity (MFI), CD86, CD80, and MHC-I expression on SM1 tumor cells markedly increased after INAPs-PTT (red) and ICG-PLGA-PTT (blue) treatment compared to controls in vitro." (PMID 31963449, 2020).
tumor (continued). "Tumor-draining lymph node (TDLN) cells were collected after 48 h of NLGP treatment and found higher per-cell MHC-I expression along with increased CD80 and CCR7 in comparison to control (Figures 5A1,A2, also in contralateral lymph node and tumor)." (PMID 32211313, 2020). "The activation status of DCs, assessed as upregulation of CD86, CD80 and CD40 when co-cultured with virus-infected tumor cells, was both virus and cell line-dependent, with some degree of activation in all cases." (PMID 31969562, 2020). "CTLA4 competes with CD28 receptors for the binding to B7 ligands (CD80 and CD86) on antigen-presenting cells (macrophages, DCs and B cells), as well as TAMs and MDSCs, inhibiting T cell activity and thus promoting tumor progression." (PMID 32823961, 2020). "Recently, PD-L1 has been shown to form a heterodimer with CD80, a shared ligand with CTLA-4 and CD28, in cis on APCs and tumor cells." (PMID 33193345, 2020). "On the contrary, CD80 and CD86 markers were negatively correlated between tumor‐infiltrating cDC2s and pDCs upon TLR stimulation, reflecting complex cross‐talks within DC subsets." (PMID 33282290, 2020). "In mice, butyrate restrains anti-CTLA-4-induced up-regulation of CD80/CD86 on dendritic cells and ICOS on T cells, accumulation of tumor-specific T cells and memory T cells." (PMID 32358520, 2020). "CD80 and CD86 are normally only expressed on APCs, but some tumor cells are able to express these co-stimulatory molecules as well." (PMID 32957644, 2020). "In that situation the MSCs needed to provide both costimuli CD80 and 4-1BB in order to induce T cells for antigen-dependent IL2 release and tumor cell killing." (PMID 32260097, 2020). "After irradiation costimulatory molecules (CD80), adhesion molecules (like intercellular adhesion molecule 1 (ICAM-1)), or stress ligand (NKG2DL) levels are increased on the surface of tumor cells." (PMID 31261963, 2019). "Matured DCs (≥ 60% upregulation of CD80, CD86, CD83, and CCR7) produced high levels of the Th1 effector cytokine, IL12-p70 (1.2 ng/ml; p < 0.0001), compared to DCs pulsed with tumour lysate, or matured with an interferon-containing cocktail alone." (PMID 30283982, 2019). "Tumors with high T-cell signatures from our clustering analysis are concordant with high expression of PD-L1, PD-L2, PD-1, CD80, CD86, CTLA-4, Tim-3, LAG3, 4-1BB, CD8, and CD4, EBV-positive status, and low tumor purity and high immune score." (PMID 30911684, 2019). "Tumor DCs from wildtype mice had higher average expression of CD40 and CD80 compared to DCs from TLR9−/− mice, suggesting that host TLR9 promotes the maturation of tumor DCs." (PMID 31619293, 2019). "The 48 h coculture initiates a pro-tumor phenotype skewing of MΦ, indicated by downregulation of IL1B, IL12, CCL18, CD80, as well as CD163, and upregulation of CLEC7A (dectin-1), CD86, CD206, and HLA-DR." (PMID 30850595, 2019). "This was accompanied by an increase in the expression of costimulatory factors CD80 and CD40 on APCs in tumor-draining lymph nodes." (PMID 31921384, 2019). "After exposure to the combination of chemotherapy and immunotherapy, more dendritic cells were present in the tumor microenvironment, which were highly activated by chemotherapy as indicated by the elevated expression of costimulatory molecules CD86 and CD80." (PMID 31362778, 2019). "Specifically, cytotoxic lymphocyte-associated protein 4 (CTLA-4) is a co-inhibitory receptor which, through binding to CD80 (B7.1) and CD86 (B7.2) ligands expressed on tumor cells and APCs, inhibits the process of T cell priming and activation." (PMID 31788395, 2019). "Butyric acid enhanced granulocytic maturation of AML cells, and just like other HDACi, induced expression of costimulatory and adhesion molecules (CD80, CD86, HLA-DR, HLA-ABC, and ICAM-1) in AML cells, inducing anti-tumor immune responses." (PMID 31739588, 2019).
tumor (continued). "It is believed that CTLA-4 impacts on the stage of T-cell activation mainly in the draining lymph nodes by removing CD80/CD86 from the surface of antigen-presenting cells, thus decreasing the ability to effectively stimulate tumor-specific T cells." (PMID 31581738, 2019). "Specifically, M1 macrophages were distinguished by higher expression of CD80—a costimulatory molecule that signals through CD28 to amplify T cell activation and contributes to anti-tumor immunity." (PMID 31552039, 2019). "T cell activation needs the activity of co-stimulatory molecules such as CD28 on T cells, bound and activated by B7-1/2 molecules (CD80/CD86) on antigen-presenting cells and tumor cells." (PMID 30987166, 2019). "For infiltrating TAMs, after adjustment for tumor purity, in LIHC, FUNDC1 was positively correlated with CD80 and CD86, and in LUSC, FUNDC1 negatively correlated with CD80, indicating the constitutive effect of TAMs on differences in tumor cell survival." (PMID 31998650, 2019). "Expression of MHC class II as well as CD80 and CD86 molecules was also higher on tumor-infiltrating macrophages from Rnf5−/− compared with WT mice." (PMID 30940817, 2019). "Stratification according to tumor stage revealed that macrophages, specifically the CD163+ ones, are more prevalent in stage II tumors, whereas CD80+ macrophages are predominant in less invasive T1 tumors." (PMID 31481956, 2019). "In addition to inducing Type 1 IFNs, co-stimulatory molecules (CD80, CD86, CD80) are also upregulated and targeting these pathways may assist in overcoming tumor-induced DC tolerance, particularly when designing therapies that manipulate the DC directly such as vaccines." (PMID 31921140, 2019). "In consideration of the role of ICOS, CD28 and CD80 genes in tumor immunity, we chose ICOS rs4404254 T>C, rs10932029 T>C, CD28 rs3116496 T>C and CD80 rs7628626 C>A SNPs to explore their potential roles in the etiology of HCC." (PMID 31235485, 2019). "Ectopic expression of these molecules and their ligands (CD80, CD86, and PD-L1) downregulates the activities of antigen-presenting cells and tumor-specific T cells through direct cell-to-cell interactions with Tregs." (PMID 30619286, 2018). "The tumor-bearing mice treated with HHT and NAR exhibited increased CD80 and CD86 expression in B220+ B cells of splenocytes as compared to untreated mice." (PMID 29844447, 2018). "The expression levels of CD80, CD86, and CD69 in B220+ B cells from splenocytes of HHT-treated mice were higher than that of control mice in two mouse tumor models." (PMID 29844447, 2018). "The level of matured dendritic cells (CD80+/CD86+ cells) in the tumor draining lymph node of PSPEI-PAA treated tumor mice were enhanced and therefore CD8+ T cells infiltration in the tumor were enriched." (PMID 30960988, 2018). "The dysregulation of PD-1 ligands (PD-L1 and PD-L2) and CTLA-4 ligands (CD80 and CD86) represents a tumor strategy to escape the immune surveillance." (PMID 30123257, 2018). "Dendritic cells isolated from the brains of tumor bearing animals were assessed for expression of known activation markers, including CD80 (B7-1), CD86 (B7-2), and I-Ab major histocompatibility complex (MHC) class II." (PMID 30211113, 2018). "Research has shown that HDACis can upregulate the expression of CD80 and CD86, hence improving tumor cell immunogenicity, promoting the elimination of tumor cells, and enhancing the treatment efficacy of antibodies targeting CTLA-4." (PMID 30558227, 2018). "Meanwhile, MHCII, CD40 and CD80 genes expression showed significant increasing in comparison to PBS; these findings suggested that DCs effectively recognized tumor antigens and efficiently presented to T cell." (PMID 29959375, 2018). "At day 17 post-tumor inoculation, QBKPN treatment increased the ratio of CD80/CD206 expression on lung macrophages, demonstrating an increase in the percentage of M1 lung macrophages." (PMID 29399400, 2018).
tumor (continued). "Like CD28, CTLA4 is able to bind to CD80 and CD86, which are expressed on the surface of tumor cells and APCs." (PMID 30558227, 2018). "As CTLA-4 has a much higher affinity to CD80 and CD86 than CD28, the outcome will also be influenced by CD80/86 expression and subsequent ligation in the TDLN and tumor sites." (PMID 30542345, 2018). "Accordingly, tumor cells are likely capable of inhibiting antitumor CD8+ T cell responses by signaling through both PD-1 and CD80." (PMID 29181416, 2017). "Wild-type and GRP78 heterozygous tumor-bearing mice were treated with tamoxifen and fixed tumors were stained for CD68 and CD80." (PMID 29113324, 2017). "As a receptor expressed on CD4+, CD8+, and regulatory T-cells, CTLA-4 competitively disrupts the axis between tumour-specific T-lymphocytes bearing CD28 receptors and stimulatory ligands CD80 (B7) and CD86 (B70) on antigen-presenting cells." (PMID 28571578, 2017). "DCs that migrated toward SN of CT26 cells particularly upregulated the activation markers CD80 and CD86 when in contact with SN of irradiated tumor cells." (PMID 28337197, 2017). "Uracil auxotrophs stimulate high-level expression of co-stimulatory molecules CD80 and CD86 as well as IL-12, and tumor antigen specific CD8+ T cell populations that mediate the long-term survival of tumor-bearing mice." (PMID 27447180, 2016). "MDSCs obtained from tumors and spleens of tumor bearing mice treated with IL-12 up-regulated the surface markers of macrophages (F4/80 and MHC II) and DCs (CD80 and CD86) suggesting differentiation into more mature, less immunosuppressive forms." (PMID 27246354, 2016). "All CD40+, CD80+, CD86+ and MHC-II+ of DCs were significantly up-regulated upon the cGAMP treatment in tumor-bearing mice." (PMID 26754564, 2016). "In our model, DC maturation with up-regulation of CD40, CD80 and CD86 was measured in tumor draining LN after IL PV-10." (PMID 27177220, 2016). "In our study, we found that MHCII I-A/I-E, CD80, and CD86 were down-regulated in TREM-2+CD11c+DCs from tumor-bearing mice." (PMID 27102437, 2016). "5AZA2 treatment has been shown to promote CD8+ T cell infiltration into the tumor in the EL4 lymphoma model, which was attributed to demethylation-induced CD80 expression on tumor cells." (PMID 27847783, 2016). "The PD-L1/PD-1 and CD80/CTLA-4 interactions inhibit CD8+ cytotoxic T-lymphocyte proliferation and survival and affect the function of tumour-infiltrating T cells, which suppress the immune system and cause peripheral immune tolerance in cancer patients." (PMID 27147225, 2016). "We subsequently measured the mRNA levels of PD-L1, CD80, CD8, TNF-α and IFN-γ via RT-PCR in ID8 tumours." (PMID 27147225, 2016). "PD-L1 binds to the programmed death-1 (PD-1) and B7.1 (CD80) proteins, and this binding can inhibit the killing of tumor cells by the immune system and decrease T-cell activation, migration, and proliferation." (PMID 27363843, 2016). "PD-L1/PD-1 and CD80/CTLA-4 interactions inhibit CD8+ cytotoxic T-lymphocyte proliferation, survival and effector functions of tumour-infiltrating T cells." (PMID 27147225, 2016). "As compared to conventional DC-tumor FCs, we have previously demonstrated that fusions generated with DCs and heat- or ethanol-treated tumor cells upregulate multiple HSPs, MHC class I molecules, MHC class II molecules, TAAs, CD80, CD86, and IL-12." (PMID 27240347, 2016). "More specifically, a lower expression of CD80 and PD-L1 of splenic-MDSC was observed when compared to tumor-infiltrating MDSC." (PMID 25869209, 2015). "In tumor, inhibition of PD-1 effectively augmented CD40+, CD80+, CD86+ cells, and especially significantly increased MHC-II+ DCs." (PMID 26573233, 2015). "These induced DAMPs played an important part in activating DCs by PDT-treated tumor cells, including phenotypic maturation (increase of surface expression of MHC-II, CD80, and CD86) and functional maturation (enhanced capability to secrete IFN-γ and IL-12)." (PMID 26625309, 2015).
tumor (continued). "In T-cell proliferation, cytokine secretion and in vivo tumor killing assays, we observed that CAR-mediated CD28 costimulation in 19-28z+ T cells is more potent than CD80 costimulation of 19z1 expressing T cells." (PMID 26110267, 2015). "CD80 and CD86 are essential for immune responses to most pathogens as well as for elimination of tumor cells by the immune system." (PMID 25371237, 2014). "Flow cytometric analysis of the harvested tumor lysate-loaded DCs revealed a phenotype characteristic of mature DCs with high expression of CD40, CD80, CD83, CD86, HLA-ABC, HLA-DR, and CCR7." (PMID 25694811, 2014). "Due to its role in maintaining tolerance, blocking CTLA-4 interaction with CD80 and CD86 was postulated to promote anti-tumor immunity." (PMID 23450201, 2013). "Forty-eight hours later, mice were euthanized and the maturation status of DC within the spleen and tumor-draining lymph nodes (TDLN) was assessed using flow cytometry by costaining for CD11c and the maturation markers CD80, CD86, I-A/I-E, and CD40." (PMID 23935927, 2013). "Seven to 10 days later tumor cells from DAC- and vehicle-treated mice were examined for CD80 expression." (PMID 23671644, 2013). "Since many immunogenic tumors lack expression of CD80 and CD86, it was postulated that tumor-infiltrating T cells would receive chronic TCR stimulation without co-stimulation leading to T cell anergy." (PMID 23450201, 2013). "While tumours from mice injected SCCVII cells contained DCs expressing either CD80 or CD86 alone, tumours formed by S12.5-injected mice contained DCs that co-expressed these two co-stimulatory molecules." (PMID 24251770, 2013). "More importantly, we found that these slow-cycling cells expressed a lower level of MHC class I molecules, but a higher level of class II, as well as a higher level of the co-stimulatory molecules CD80 and CD86, compared with conventional tumor cells." (PMID 23270473, 2012). "Exposure of primary CLL cells to lenalidomide in vitro leads to the induction of costimulatory molecules like CD80, CD86, and FASL on the tumor cells, restoring immunological synapse formation and improving autologous tumor cell recognition by T cells." (PMID 22888354, 2012). "By day 7, IFNγ, CSF2, CXCL10, GZMB, PTGS2, TNFα, CD80, CCL22, IL12a, IL13, IL1b, IL6, NOS2, and CTLA4 were significantly upregulated in the tumor-bearing mice bladders and AGTR2 and GATA3 were downregulated." (PMID 22013484, 2011). "Transduced DCs, which have been rendered insensitive to TGF-β, maintain their normal phenotype, present upregulated expression of surface costimulatory molecules (CD80/CD86) and induce potent tumor-specific cytotoxic T lymphocyte responses in vivo." (PMID 22190971, 2011). "DCs were evaluated for antigen uptake, and following maturation with LPS and IFN-gamma, DCs were assessed for expression of CD80, CD40, CD86, ICAM-1 and CCR7, production of IL-12p70 and IP-10, and induction of tumor-specific T-cell responses." (PMID 22194898, 2011). "However, it has been reported that Treg from tumor-bearing mice may impair the expression of DC costimulatory molecules CD80, CD86, and CD40, suppress DC production of proinflammatory cytokines IL-12 and TNF-α, and inhibit their ability to induce T-cell activation in vitro." (PMID 22110524, 2011). "These tumor cells were positive to the surface markers CD19, B220, CD5 and IgM, and also expressed the co-stimulatory molecules CD80, CD86 as well as CD117." (PMID 21269511, 2011). "Treatment with CT extract maintained the high profile of cell surface markers, such as CD80, CD86, MHC-I and MHC-II on the CD117+-derived CDs in the presence of tumor antigen." (PMID 19001481, 2011). "The expression of CD80 and CD86 co-stimulatory molecules were also decreased in the RBP-J-/- DCs compared with the RBP-J+/- DCs after the tumor antigens stimulation." (PMID 20420708, 2010).